SNORD92 (small nucleolar RNA, C/D box 92)
Synonyms: HBII-316
Gene: Small nucleolar RNA gene on chromosome 2 (28,913,664 to 28,913,748, forward strand). Ensembl gene ENSG00000264994.
Gene Ontology:
Biological process: RNA processing
Cellular component: nucleolus
Homologues: Orthologues: chimpanzee SNORD92 (100% identical), macaque SNORD92 (100% identical), pig SNORD92 (98% identical), rabbit SNORD92 (96% identical), mouse Snord92 (95% identical), guinea pig SNORD92 (94% identical), rat Snord92 (88% identical). Paralogues in human: SNORD53 (65% identical), SNORD53B (59% identical).
Diseases named in the same sentence as SNORD92 in open-access papers:
SNORD92 is named in the same sentence as 2 diseases in open-access papers, as found by Europe PMC text mining. Sharing a sentence is not in itself a finding about the gene and the disease.
SNORD92 shares sentences with these, for which no sentence is quoted: gastric cancer (1 paper); tumor (1).